ETS1 (ETS proto-oncogene 1, transcription factor)
Diseases named in the same sentence as ETS1 in open-access papers (continued):
Sharing a sentence is not in itself a finding about the gene and the disease.
breast carcinoma (continued). "Consistent with human cell line data, Ets1 expression was negatively correlated with Dnmt3a and Dnmt3b in normal specimens, while Ets1 level is positively correlated with Apobec3c in human breast cancer specimens." (PMID 30467308, 2018). "Another study also demonstrated that silencing of miR-125b1 leads to the activation of the ETS1 proto-oncogene resulting in worse prognosis in breast cancer patients." (PMID 28435518, 2017). "For instance, miR-199a targets the transcription factor Ets-1 in breast carcinoma and hence downregulates the expression of β 1-integrin, leading to an increase in the invasive abilities of the tumor cell." (PMID 29215551, 2017). "It was also reported that miR-124 inhibited cellular proliferation and invasion by targeting Ets-1 in breast cancer cells." (PMID 27175587, 2016). "ETS1 is involved in breast cancer where it regulates genes that are important for metastasis and tumor progression." (PMID 26627005, 2015). "Upregulated ETS-1 has been observed in breast cancer, lung cancer, ovarian cancer, colorectal cancer and malignant melanoma." (PMID 25421630, 2015). "ETS-1 is overexpressed in invasive breast cancer and is correlated with the poor prognosis of breast cancer patients." (PMID 25421630, 2015). "Recently, it was reported that ETS1 gene is overexpressed in drug-resistant human breast cancer cell lines." (PMID 24602286, 2014). "This study demonstrates that drug resistance can be effectively reversed in adriamycin-resistant breast carcinoma cells through delivery of siRNAs targeting ETS1." (PMID 24602286, 2014). "Given the convergence of four breast-cancer-associated genes (EMSY, ETS-1, KDM5B, and miR-31) with overlapping biological roles, this pathway offers a number of avenues for therapeutic intervention." (PMID 24582497, 2014). "Erythroblastosis virus E26 oncogene homolog 1 (ETS1) is involved in the drug resistance of various cancer cells, and is overexpressed in drug-resistant human breast cancer cell lines." (PMID 24602286, 2014). "Recently, it was reported that Erythroblastosis virus E26 oncogene homolog 1 (ETS1) gene is over-expressed in drug-resistant human breast cancer cell lines." (PMID 24602286, 2014). "The purpose of this study was to explore the role of transcription factor Ets1 in estrogen receptor α (ERα)-positive breast cancer progression." (PMID 23874775, 2013). "In support of this, we identified increases in colony formation and cellular motility upon Ets1 expression in ERα-positive human breast cancer cells." (PMID 23874775, 2013). "To examine the functional consequences of decreased Ets-1 expression in breast cancer cells, we examined glycolytic dependence and oxygen consumption in MDA-Ets1KD cells." (PMID 24280356, 2013). "In agreement with the finding that restoring miR-125b expression inhibited breast cancer cell proliferation by blocking Ets1, high levels of Ets1 correlated with poor patient prognosis." (PMID 23325049, 2013). "Ets1-expressing human breast cancer cells demonstrated increased cellular proliferation, clonogenic growth, migration and invasion." (PMID 23874775, 2013). "In breast cancer, the promoter of miR-125b was methylated and silenced, which allowed the levels of the miR-125b target oncoprotein (Ets1) to rise." (PMID 23325049, 2013). "Collectively, this study confirms the important role of Ets-1 in the regulation of cancer energy metabolism in ovarian and breast cancers." (PMID 24280356, 2013). "In this study, we were able to repeat these findings in a breast cancer Ets-1 knockdown model, giving more strength to our theory that Ets-1 is integral in regulating cancer cell metabolism." (PMID 24280356, 2013). "We expressed human Ets1 or empty vector in four human ERα-positive breast cancer cell lines and observed increased colony formation." (PMID 23874775, 2013).
breast carcinoma (continued). "To extend our findings to another cancer type, we developed an Ets-1 knockdown breast cancer cell model, which displayed decreased glycolytic dependence and increased oxygen consumption following Ets-1 knockdown confirming our earlier findings." (PMID 24280356, 2013). "Recent studies reveal the post-transcriptional regulation of Ets1 by miR-125b in breast cancer cells, and by miR-200b in endothelial cells." (PMID 23383271, 2013). "The inverse relationship observed between the expression levels of these genes in our ovarian and breast cancer cell models suggest that Ets-1 regulates the expression of these factors in a similar manner in breast cancer cells." (PMID 24280356, 2013). "As we have previously shown that Ets-1 regulates energy metabolism in ovarian cancer cells, for this study we endeavored to extend those findings to breast cancer cells." (PMID 24280356, 2013). "Both Ets1 and Ets2 expression are correlated with decreased disease-free survival in breast cancer patients and a dominant negative Ets construct can inhibit the anchorage independent growth of breast cancer cell lines." (PMID 23874775, 2013). "In the current study, we examine the effect of Ets1 expression on human breast cancer cell lines using both in vitro and in vivo analyses." (PMID 23874775, 2013). "The Ets-1 transcription factor is a candidate breast cancer oncogene that regulates the expression of genes involved in tumor progression and metastasis." (PMID 22971289, 2012). "Accordingly, both forced NOS2 over-expression and exposure to NO-donors resulted in significant Ets-1 transcriptional activation in ER- breast cancer cells." (PMID 22971289, 2012). "Together, these data provide novel evidence that NO signaling promotes an aggressive breast cancer phenotype by activating the oncogenic Ets-1 transcription factor." (PMID 22971289, 2012). "RNA knock-down of Ets-1 suppressed NO-induced expression of selected basal-like breast cancer markers such as P-cadherin, S100A8, IL-8 and αβ-crystallin." (PMID 22971289, 2012). "Because NOS2 expression resulted in Ets-1 (thr 38) phosphorylation, we also examined the effect of NO signaling on Ets-1 activation in human ER- breast cancer cell lines treated with NO releasing compounds." (PMID 22971289, 2012). "TF Ets-1 has been found to have significant prognostic value for relapse-free survival as an independent predictor of poor prognosis in breast cancer." (PMID 20181230, 2010). "In a study of 123 patients with primary breast cancer followed for 62 months, Ets-1 expression correlated strongly with VEGF expression and was an independent predictor of poor prognosis." (PMID 20454645, 2010). "It is of interest to note that a number of the TFs that bind in the exon -2a cluster have indeed been implicated in breast cancer progression, including LEF, ETS-1, ETS-2 and NFAT3." (PMID 19357769, 2009). "Overexpression of peroxiredoxin 6 leads to a more invasive phenotype and metastatic potential in human breast cancer, at least in part, through regulation of the levels of uPAR, Ets-1, MMP-9, RhoC and TIMP-2 expression." (PMID 17980029, 2007). "It has been reported that Ets-1 was overexpressed in a variety of human malignancies, including breast cancers." (PMID 17980029, 2007). "Conversely, experimental inhibition of PRDX6 expression decreased the invasive and potential potential of breast cancer cells, partially through regulation of uPAR, Ets-1, MMP-9, RhoC and TIMP-2 expression." (PMID 17980029, 2007). "All these results indicate that PRDX6 promotes breast cancer progression, partially through upregulation of uPAR, Ets-1, MMP-9 and RhoC expression and downregulation of TIMP-2 expression." (PMID 17980029, 2007). "We also related levels of Ets-1 to the established prognostic factors for breast cancer and factors involved in tumour progression, that is, urokinase plasminogen activator (uPA) and human epidermal growth factor receptor 2 (HER-2/neu)." (PMID 15365563, 2004).
breast carcinoma (continued). "Ets-1 mRNA was expressed in similar proportions of fibroadenomas (30 out of 42, 71%) and primary breast carcinomas (131 out of 179, 73%) (P, NS)." (PMID 15365563, 2004). "The aim of this study was to investigate the expression of Ets-1 in a large panel of human breast cancers and relate its levels to the parameters of tumour progression and metastasis." (PMID 15365563, 2004). "Using RT–PCR, Ets-1 mRNA was detected in 30 out of 42 (71%) fibroadenomas and 131 out of 179 (73%) primary breast carcinomas." (PMID 15365563, 2004). "Our results show that certain forms of the Ets-1 protein, that is, p52 and p51, are expressed at much higher levels in breast cancer compared to fibroadenomas." (PMID 15365563, 2004). "We found strong Ets-1 staining in the primary breast carcinoma tissue sections, especially on the tumour cells." (PMID 15365563, 2004). "We conclude that, while at the mRNA level, Ets-1 was found at similar levels in fibroadenomas and primary breast carcinomas, higher protein levels were detected in the cancers compared to the benign specimens." (PMID 15365563, 2004). "In this investigation, Ets-1 mRNA was found to be expressed at similar levels in breast carcinomas and fibroadenomas." (PMID 15365563, 2004). "Moreover, in our breast cancer PDO samples, ETS1 expression was negatively associated with dasatinib (r = −0.3270, p = 0.0139)." (PMID 41462902, 2025). "In a number of breast cancers, Ets‐1 is overexpressed, which is correlated with a poor prognosis." (PMID 39778077, 2025). "Indeed, Ets‐1 has been demonstrated to play an important role in the progression of breast cancer by promoting metastasis/invasion, epithelial‐to‐mesenchymal transition (EMT), and neo‐angiogenesis." (PMID 39778077, 2025). "ETS-1 directly activates cyclin D1 transcription by binding to its promoter, resulting in increased Cyclin D1 protein levels, which accelerate the progression through the G1/S checkpoint and increase breast cancer cell proliferation." (PMID 40181983, 2025). "The effectiveness of PARPi in only Ets‐1 expressing breast cancer cells lead us to suggest that Ets‐1 expression may represent a biomarker potentially able to identify the most sensitive breast cancer cells for treatment with PARPi." (PMID 39778077, 2025). "We may suggest that PARP‐1 inhibition increased oxidative DNA damage only in breast cancer cells expressing Ets‐1." (PMID 39778077, 2025). "In this sense, it is interesting to test whether Ets‐1 knockdown can cancel the PARPi effect in Ets‐1‐expressing breast cancer cells." (PMID 39778077, 2025). "ETS-1 plays a key role in regulating breast cancer cell proliferation and metastasis." (PMID 40181983, 2025). "ETS1 overexpression led to reduced ROS along with increased expression of glutathione peroxidase, thereby improving the response to oxidative stress in ovarian and breast cancers." (PMID 36760475, 2023). "Interestingly, in a study with breast cancer cells, Ets-1 overexpression was inhibitory to in vitro soft-agar colony growth in mouse mammary tumor cells." (PMID 35789155, 2022). "Our extensive analysis of PTPN18 in EMT and metastasis indicated that nuclear PTPN18 but not cytoplasmic PTPN18 antagonized TGFβ signaling-regulated EMT and reduced the metastatic ability of breast cancer cells through regulation of ETS1 phosphorylation in breast cancer." (PMID 35982039, 2022). "Candidate pathways were constructed starting from the estrogen receptor ESR1 gene and targeting breast cancer-associated transcription factors, such as JUN, FOS, STAT1, STAT3, STAT5A, ELK1, and ETS1 (Target transcription factors were pre-identified by GibbsOS19)." (PMID 33432018, 2021). "So far, it remains unclear how ELF3 inhibits ZEB1 promoter activation by ETS1 in breast cancer cells." (PMID 33712555, 2021). "Interestingly, knockdown of ETS1 expression significantly increased proliferation capacity of breast cancer cells measured by Ki-67 expression." (PMID 32477936, 2020).
breast carcinoma (continued). "ETS1 has shown dichotomous roles as an oncogene and a tumor suppressor gene in diverse cancers, but its functionality in breast cancer tumorigenesis still remains unclear." (PMID 32477936, 2020). "Since MDA-MB-231 is a triple negative breast cell line that can only represent a specific subset of breast cancer, we tried to confirm whether ETS1 inhibits the proliferation of tumor cells with MCF-7 cells (ER+, PR+ and HER2− cell)." (PMID 32477936, 2020). "Next, to assess whether ETS1 expression level has clinical implications, we classified breast cancer patients into two groups based on ETS1 expression in BRCA specimens (ETS1high and ETS1low)." (PMID 32477936, 2020). "The transcription of NTNG2 in breast cancer is positively regulated by ETS1 (r = 0.2971), suggesting that NTNG2 may be related to the development of breast cancer." (PMID 32251318, 2020). "ETS1 functions as an oncogene and is a crucial regulator of phenomena involved in tumorigenesis, such as the mesenchymal phenotype in various tumors, including head and neck squamous cell carcinoma, breast cancer, prostate cancer, and glioblastoma." (PMID 33042835, 2020). "Similarly, a repressive effect of ETS1 based on soft agar assays was illustrated in breast cancer cell growth, collectively denoting that the influence of ETS1 on cellular growth depended on tissue context and tumor type." (PMID 31438961, 2019). "Intensive studies have shown that the MEK/ERK signaling pathway could regulate ETS-1 through phosphorylation at threonine 38 in lung and breast cancers." (PMID 31118072, 2019). "Indeed, TGFβ1‐induced expression of ETS1 and breast cancer cell migration was blocked by knockdown of ETS1." (PMID 30004628, 2018). "Moreover, enhanced level of Nfatc2 and Nfkb1 positively correlated with Ets1 expression in the human breast cancer specimens." (PMID 30467308, 2018). "Ets-1 promotes the growth and metastasis of different cancer cell lines, while knockdown of Ets-1 inhibits cell transformation and reverses the multiple drug resistance of breast cancer cells." (PMID 29773901, 2018). "Accordingly, Ets1 could be a conceivable therapeutic target especially in the triple-negative/basal-like breast cancers (TN/BLBC) that show Ets1high expression profile compared with non-TNBC cells." (PMID 30467308, 2018). "In our study, we used public data deposited in TCGA database and performed survival analysis in breast cancer with different ETS1 expressions, and found high ETS1 expression was significantly associated with poor survival in breast cancer, which was consistent with previous findings." (PMID 29950928, 2018). "Inhibition of this interaction could be a therapeutic approach to reduce Ets1 levels and Ets1-mediated tumor invasiveness of breast cancer cells." (PMID 30467308, 2018). "However, it is still unclear which types of transcriptional factors and cis-acting regulatory elements cooperatively regulate transcriptional activity of Ets1 gene expression, especially in breast cancer cells." (PMID 30467308, 2018). "ETS1 has been reported to be upregulated in a variety of tumors and could be considered as a prognostic marker in patients with tumors including breast cancer, ovary and cervix carcinoma and hepatocellular carcinoma." (PMID 26177288, 2015). "Based on these findings, they proposed that miR-124 and Ets-1 might serve as a therapeutic agent in breast cancer." (PMID 25924779, 2015). "High level of ETS-1 was identified in breast cancer, ovarian cancer and cervical carcinoma." (PMID 26122040, 2015). "However, we predicted that Ets1 and Ets2 are the potential binding proteins of the Ets site based on their overexpression in breast carcinomas like MCF-7 used in this study and their regulation by PMA through PKC pathway activation." (PMID 25490397, 2014).
breast carcinoma (continued). "The basal levels of MMP-1 and MMP-9 are increased in various breast cancer cells, including MCF7, in response to heregulin-β1 via activation of MAPK/ERK pathway and overexpression of Ets1 in ErbB2 expressing breast cancer cells increases the expression of MMP-1." (PMID 24709902, 2014). "The ETS-1 and MMPs often aberrant express in breast cancer, lung cancer and prostate cancer." (PMID 24857950, 2014). "These indicated that, FBI-1 may modulate the HER2 signaling and participate in breast cancer progress via ETS-1." (PMID 24857950, 2014). "Furthermore, it is interesting to note that two components of this pathway, namely ETS-1 and KDM5B, have themselves been implicated in breast cancer." (PMID 24582497, 2014). "Based on these interactions, we hypothesized that Ets1 could serve as an initiating switch reducing the dependence of breast cancer cell lines on ERα signaling and eventually leading to hormone independence." (PMID 23874775, 2013). "We observed that Ets-1 regulation of cancer-specific metabolic changes is a phenomenon that also exists in breast cancer cells, thus complementing our previous work and suggesting that Ets-1 regulation of metabolism may be a generalized phenomenon." (PMID 24280356, 2013). "Furthermore, overexpression of NOS2 and experimental exposure to NO resulted in Ets-1 (threonine 38) phosphorylation and increased transcriptional activity in ER- breast cancer cell lines." (PMID 22971289, 2012). "Thus, we examined the role of Ets-1 in NO signaling and NO-induced phenotypes in ER- human breast cancer cells." (PMID 22971289, 2012). "Ets-1 is an oncogenic transcription factor involved in the progression of breast cancer." (PMID 22971289, 2012). "Both ETS1 and CIP2A have been associated with clinical aggressivity in breast cancer." (PMID 21445343, 2011). "In addition, ETS-1 mRNA overexpression appears to be a strong independent predictor of poor prognosis in primary human breast cancers." (PMID 21871131, 2011). "Ets-1 is expressed in 53% of tumors of patients with newly diagnosed breast cancer." (PMID 20454645, 2010). "VEGF and Ets-1 are also highly expressed in breast carcinoma." (PMID 20454645, 2010). "Ets1 expression in tumor cells has been found to correlate with the grade of invasiveness in human tumor tissues and correlates with a degree of invasiveness in breast cancer cell lines." (PMID 19930697, 2009). "Since p52, p51 and p33 correlate with uPA levels, these forms of Ets-1 may play a role in breast cancer metastasis." (PMID 15365563, 2004). "Given that both IL-8 and ETS1 expression correlate with the invasive phenotypes of cancer cells and angiogenesis, our study provides further evidence of the multifaceted promotion of breast cancer progression by SHP2, in this case via upregulation of the pro-tumorigenic cytokine IL-8." (PMID 35739379, 2022). "Moreover, NFKB1/RELA induces breast cancer progression by upregulating ETS1." (PMID 34335799, 2021). "Moreover, the expression of SP100 could regulate the transcriptional activity of ETS1 and further influence the cell invasion in breast cancer." (PMID 32431729, 2020). "Interestingly, ETS1 and ELK1 have been shown to coordinately upregulate CIP2A, which encodes cancerous inhibitor of protein phosphatase 2A and leads to progression of gastric, cervical and breast cancer." (PMID 32079144, 2020). "Moreover, given the intense interest in understanding the biomarkers for predicting breast cancer prognosis, our findings indicate that evaluating ETS1 level in tumors may be an important predicator for BRCA patients." (PMID 32477936, 2020). "Thus, down-regulation of ETS1 via shRNA stably transfection might be a promising treatment for MDR breast cancer therapy." (PMID 29950928, 2018).